WFS1 (wolframin ER transmembrane glycoprotein)
Diseases named in the same sentence as WFS1 in open-access papers (continued):
Sharing a sentence is not in itself a finding about the gene and the disease.
type 2 diabetes (continued). "For example, several GWAS loci for type 2 diabetes contain genes known to harbour causal coding variants for rare Mendelian syndromes related to type 2 diabetes (e.g. HNF1A, HNF1B, WFS1, PPARG, KCNJ11, HNF4A, GCK)." (PMID 26702037, 2015). "This has been shown, e.g. for SNPs in TCF7L2 and WFS1 which become more and more relevant during the progression of prediabetes stages towards clinically overt type 2 diabetes." (PMID 22768041, 2012). "And we also found the WFS1 rs10010131 and FTO rs8050136 showed trends towards association to type 2 diabetes in our samples (0.05<P<0.1)." (PMID 19862325, 2009). "In another study, allele-specific expression of several genes in islets (ANPEP, CAMK2B, HMG20A, KCNJ11, NOTCH2, SLC30A8 and WFS1) showed that even subtle changes of gene dosage may have significant consequences for development of type 2 diabetes." (PMID 30497374, 2018). "WFS1 has also been linked to an autosomal dominant form of low-frequency sensorineural hearing loss (LFSNHL), autosomal dominant optic atrophy (ADOA), type 2 diabetes and psychiatric problems." (PMID 25289672, 2014). "Moreover, it appears that effective treatment for WFS1 could also be repurposed for common conditions, like type 2 diabetes and neurodegenerative conditions." (PMID 37759745, 2023). "The results of studies suggest that the WFS1 gene may be the candidate gene for type 2 diabetes." (PMID 35207731, 2022). "In stage 1, 88 SNPs were genotyped in 1,251 patients with type 2 diabetes, and we found that ADAMTS9-AS2 rs4607103, WFS1 rs10010131, CDKAL1 rs7756992, VPS26A rs1802295 and IDE-KIF11-HHEX rs1111875 were significantly associated with DR." (PMID 28821857, 2017). "Furthermore, recent studies have described patients with WS1 and type 2 diabetes (T2DM), suggesting a possible link between WFS1 gene, among other genes, with T2DM." (PMID 36835101, 2023). "We found that our false positive associations with genes WFS1, HNF4A, NPHP4, and TXNL4B were reported to be associated with Type II Diabetes in GWAS Catalog while the others were not." (PMID 33206638, 2020). "Our prediction identified the m6A genes HNF1B, HNF1A, WFS1, and IRS2 as the potential disease genes, which could provide a new clue to study the role of m6A in type 2 diabetes." (PMID 30601803, 2019). "Our finding also supported that WFS1 and FTO might participate in the pathogenesis of type 2 diabetes, although the effects we detected on rs10010131 and rs8050136 were not statistically significant." (PMID 19862325, 2009). "Recently, several genome-wide and candidate gene association studies have identified many novel genetic loci for type 2 diabetes (T2D); among these genes, CDKAL1, IGF2BP2, SLC30A8, CDKN2A/B, HHEX, FTO, TCF2, KCNQ1, and WFS1 are the most important." (PMID 20509872, 2010).
Wolfram-like syndrome (26 papers, 2016 to 2026). "The patient had a novel mutation, which is a missense heterozygous mutation of 650 tyrosine to cysteine in WFS1; thus, a diagnosis of Wolfram-like syndrome (WFLS) was suspected." (PMID 42040055, 2026). "Rs367547063 in WFS1, a gene implicated in Wolfram and Wolfram-like syndromes and ADNSHL, was significantly associated with H-aid (OR = 10.0) and H-both (OR = 4.1)." (PMID 40055553, 2025). "Subject #15 was diagnosed with Wolfram-like syndrome after detection of a monoallelic pathogenic WFS1 variant through whole genome sequencing, which was performed because of unusual MRI features." (PMID 41245872, 2025). "Responsible for WS, variants of WFS1 were also associated with different forms of inherited deafness and Wolfram-like syndrome." (PMID 37386014, 2023). "Dominant missense mutations in human WFS1 gene are also associated with a distinct Wolfram-like syndrome that includes hypotonia." (PMID 35325133, 2022). "WFS1 pathogenic variants have been linked to Wolfram and Wolfram-like syndromes, which include cases with just one pathogenic variant in heterozygosis not meeting the WS diagnostic criteria." (PMID 36330437, 2022). "Variants of WFS1 are also associated with AD Wolfram-like Syndrome and AR Wolfram Syndrome [MIM: 614296 and 222300]." (PMID 34837038, 2022). "A dominant mutation in the WFS1 gene was also described in connection with sensorineural hearing loss, deafness, and optic atrophy [Wolfram-like syndrome (WFSL)]." (PMID 27217304, 2016). "Without genetic confirmation, it is not possible to differentiate between Wolfram syndrome type 1 (WFS1 gene mutation), Wolfram syndrome type 2 (WFS2 gene mutation), Wolfram-like syndrome (heterozygous WFS1 mutation), and maternally inherited diabetes and deafness (MIDD)." (PMID 41306145, 2025). "Based on a systematic review and the present study, a total of 62 WFS1 variants causing DFNA6/14/38 or wolfram-like syndrome were identified: 7 were in the N-terminal cytoplasmic domain, 12 were in the transmembrane domain, and 43 were in the C-terminal ER luminal domain." (PMID 37041640, 2023). "Different pathogenic variants in WFS1 may give rise to different disease phenotypes, but genotype–phenotype correlations for either WS or Wolfram-like syndrome have been elusive, especially due to the low number of described patients and the large number of reported variants." (PMID 36330437, 2022). "A heterozygous mutation in the Wolfram syndrome type 1 gene (WFS1) causes autosomal dominant nonsyndromic hereditary hearing loss, DFNA6/14/38, or Wolfram-like syndrome." (PMID 29529044, 2018). "Heterozygous mutations in the Wolfram syndrome type 1 gene (WFS1) are responsible for one form of ADNSHL, DFNA6/14/38 (MIM #600965), and Wolfram-like syndrome (MIM #614296)." (PMID 29529044, 2018).
depression (17 papers, 2012 to 2025). "WFS1 mutations lead to reduced import in Ca 2+, causing mitochondrial dysfunction, which has been linked to depression." (PMID 41446462, 2025). "The scoping review indicates that anxiety, depression, apathy, and behavioral dysregulation are recurrently described in individuals carrying WFS1 variants." (PMID 41008710, 2025). "The exacerbation of obesity and depression‐like behaviors in HFD‐induced obese mice due to WFS1 deficiency was effectively relieved by riluzole." (PMID 39258564, 2024). "In summary, this study revealed the role of neural‐specific WFS1 deficiency in exacerbating the vicious cycle of obesity and depression in HFD mice." (PMID 39258564, 2024). "Our data indicate that Wfs1 and related molecules were predicted to be associated with the pathological process of depression." (PMID 33552119, 2020). "Here, we report that Wfs1, a gene that can cause depression, is co-expressed with Ntf3, Penk, and Wnt7a in supragranular 2/3 pyramidal neurons in the mPFC." (PMID 26371510, 2015). "Because of the apparently important role of serotonin (5-HT) and noradrenaline (NA) in the treatment of depression, we sought to study these neurotransmitter systems in Wfs1-deficient mice using pharmacological, genetic and biochemical methods." (PMID 23914152, 2013). "Thus, our results reveal mechanistic insight into the vicious cycle of obesity and depression induced by neural‐specific WFS1 deficiency and propose a therapeutic approach to counteract obesity and depression with riluzole." (PMID 39258564, 2024). "Additionally, WFS1 is reported to be closely associated with multiple psychiatric illnesses, including severe depression, psychosis, obsessive-compulsive disorder, and suicidal behavior." (PMID 38764027, 2024). "A study in mice further confirmed that WFS1 mutation is causative for depression." (PMID 37399203, 2023). "Given the prominent expression of Wfs1 in the cortex, and the extensive literature documenting a role for the PFC in depression and resilience to stress, we were particularly interested in phenotypes that occur specifically as a consequence of Wfs1 mutation in the cortex." (PMID 26371510, 2015). "Previous reports have indicated that there may be a role of the WFS1 gene in depression and suicide attempts, as carriers of one WFS1 mutation had a greater risk for lifetime psychiatric symptoms." (PMID 26025012, 2015). "Therefore, Wfs1/UBTF/mmu-mir-17-5 may play an important role in the pathogenesis of depression caused by long-term stress." (PMID 33552119, 2020). "Therefore, it is possible that similar changes may occur in humans due to the invalid function of the WFS1 gene and this may explain an increase in the susceptibility of these patients to depressive disorders." (PMID 23914152, 2013). "For example, the CRISPR/Cas9 system can create WFS1-knockout brain organoids from hESCs, revealing the pathogenesis of the vicious obesity-depression cycle." (PMID 41359105, 2025). "The stdy shows that neural‐specific WFS1 deletion exacerbates high‐fat diet‐induced obesity and depression via modulating zinc homeostasis." (PMID 39258564, 2024). "In this study, neural‐specific WFS1 deficiency exacerbates the vicious cycle of obesity and depression in mice fed a high‐fat diet (HFD), positioning WFS1 as a crucial factor in this cycle." (PMID 39258564, 2024). "To recapitulate the pivotal role of WFS1 in human obesity and depression, we employed a 3D culture system for deriving human cerebral organoids in vitro." (PMID 39258564, 2024). "CKO mice showed Wfs1 deficiency and significantly increased expression of Atf4 and Znt3 in the hippocampus, cortex, and hypothalamus, suggesting the crucial role of Wfs1 in regulation of vicious cycle of obesity and depression." (PMID 39258564, 2024).
depression (continued). "The present study highlights and identifies Wfs1 and related molecules in the hippocampus as new potential targets for depression and improves our understanding of molecular mechanisms underlying depression pathophysiology." (PMID 33552119, 2020). "Based on a series of bioinformatics analyses, we identified Wfs1 and its related molecules as potential genetic targets for depression." (PMID 33552119, 2020). "The molecular mechanism of Wfs1 and its related molecules participating in depression need to be further investigated." (PMID 33552119, 2020). "Here, we have reported the change of the Wfs1 mRNA level in the CUMS model, suggesting that Wfs1 is involved in the early state and the long-term development of depression." (PMID 33552119, 2020). "Wfs1 is an ER membrane protein and expressed specifically in the adult mouse brain regions relevant to stress and depression, including superficial layers of the cerebral cortex, the central extended area of the amygdala, and the hippocampus." (PMID 33552119, 2020). "The present analysis supports a possible contribution of hippocampal Wfs1 to depression in the hippocampus is in its beginning stages." (PMID 33552119, 2020). "The demonstration that expression of Wfs1 occurs in superficial layer 2/3 pyramidal cells in the prefrontal cortex of mice is interesting with regard to relationship between stress and depression." (PMID 26371510, 2015). "Our cohort also had notable depression and anxiety, similar to findings in advanced WFS and anxiety behaviors found in animal models of WFS (wfs1-deficient mice)." (PMID 22792385, 2012). "The WFS1/activating transcription factor 4 (ATF4)/zinc transporter 3 (ZNT3) signaling axis is implicated in palmitate-induced apoptosis, which is associated with obesity and depression, and the drug riluzole can target this axis to maintain zinc homeostasis." (PMID 41359105, 2025). "Here, we utilize 3D human cerebral organoids and 2D neural progenitor cells derived from human embryonic stem cells harboring WFS1 deficiency and Wfs1 conditional knockout mice (Wfs1flox/flox X Nestin‐Cre, CKO) exposed to HFD to examine the vicious cycle of obesity and depression." (PMID 39258564, 2024). "On the other hand, heterozygous mutation of WFS1 does not lead to WS1 but increase the risk of depression by 26 fold." (PMID 37399203, 2023). "To recapitulate the psychiatric disturbances in patients, we conducted a series of behavioral studies including forced swimming test (depression), novel object test (recognition memory) and water maze test (spatial memory) in the Wfs1 conditional knockout mice (CKO mice)." (PMID 36750736, 2023). "In conclusion, Wfs1 and related molecules are key genes involved in depression." (PMID 33552119, 2020). "Our results indicate, therefore, that loss of Wfs1 in forebrain neurons does not disrupt baseline learning or cognitive flexibility but renders the animals vulnerable to stress-induced depression-related behaviors." (PMID 26371510, 2015). "Further experiments are required to investigate the possibility that using drugs to manipulate cells that express Wfs1 could protect against the harmful effects of stress, or even treat existing episodes of depression." (PMID 26371510, 2015). "Though not all mutations in WFS1 gene cause WS, carriers of WFS1 gene mutations have a 26 times higher risk for psychiatric diseases such as depression and bipolar disorder." (PMID 26379490, 2015). "Patients without WS, but exhibiting bipolar disease, major depression, and schizophrenia have been found to carry mutations in WFS1 gene." (PMID 26379490, 2015). "Heterozygous carriers of WFS1 mutations, not affected with WS, have a 26-fold higher likelihood of psychiatric hospitalization mainly due to depression." (PMID 23914152, 2013). "However, the detailed mechanism of Wfs1 in depression requires further investigations." (PMID 33552119, 2020).
depression (continued). "Considering the efficacy of antidepressant drugs in the treatment of depression, we studied the effects of paroxetine (a selective 5-HT reuptake inhibitor) and imipramine (a 5-HT and NA reuptake inhibitor) in the tail suspension test (TST) and forced swimming test (FST) in Wfs1-deficient mice." (PMID 23914152, 2013). "Our results reveal that neural‐specific WFS1 deletion exacerbates HFD‐induced obesity and depression via modulating zinc homeostasis." (PMID 39258564, 2024). "Thus, a WFS1‐ZnT3‐Zn2+ axis critical is demonstrated for the vicious cycle of obesity and depression and that riluzole may have the potential to reverse this process against obesity and depression." (PMID 39258564, 2024). "Although there is no current evidence to prove their direct role in depression, the target gene Wfs1 of mmu-mir-17-5p is considered a candidate genetic marker related to the relief of depression." (PMID 33552119, 2020).
insulin-dependent diabetes mellitus (16 papers, 2008 to 2025). "A recent study used a rat model to demonstrate that deletion of exon 5 of the Wfs1 gene, which results in the loss of 27 amino acids from the Wfs1 protein, caused insulin-dependent diabetes, optic nerve atrophy, and medullary degeneration." (PMID 29357349, 2018). "Heterozygous variation of WFS1 can also lead to isolated non-insulin-dependent diabetes (MIM 125853), cataracts (MIM 116400), and deafness associated with pathogenic mutation (automatic dominant 6/14/38) (MIM 600965)." (PMID 36967753, 2023).
cataract (13 papers, 2017 to 2026). Partial or complete opacity of the crystalline lens of one or both eyes that decreases visual acuity and eventually results in blindness. "Recently, La Morgia and coauthors suggested that WFS1 variants can affect mitochondrial function and that in turn will affect calcium regulation, a known cataract risk factor." (PMID 37493686, 2023). "The presence of cataracts in Wfs1-deficient rats further supports that these rats developed WS." (PMID 28860598, 2017). "Though the WFS1 c.2070_2079del variant is speculated to yield a loss-of-function mutant, at this moment, we are unable to specify the genetic contribution of WFS1 on cataracts." (PMID 36843716, 2023). "We cannot exclude the decline in visual acuity in saline-treated Wfs1 KO rats as being due to severe progression of cataracts." (PMID 34831417, 2021). "Cataracts have been suggested as a phenotypic marker of WS30; therefore, we evaluated the incidence of cataracts in Wfs1-ex5-KO232 rats." (PMID 28860598, 2017). "Although it is not a main feature of WFS1, other studies have found heterozygous WFS1 mutations that were associated with cataracts." (PMID 33946243, 2021). "Additionally, a positive correlation was observed between insulin dose (IU/kg/day) and cataract score in saline-treated Wfs1 KO rats (R2 = 0.396, p < 0.01) and in liraglutide-treated Wfs1 KO rats (R2 = 0.271, p < 0.05)." (PMID 34831417, 2021). "Cataract severity evaluated in 13- and 17-month-old animals, was increased at the age of 13 months in Wfs1 KO rats compared to WT littermates (p < 0.001), and liraglutide treatment was able to protect Wfs1 KO animals from developing cataracts." (PMID 34831417, 2021). "It was proved that the C505S mutation of WFS1 contributes greatly to the occurrence of iris coloboma and corroborated that the CRYGD p.P24T possibly leads to cataract, although CRYGD p.P24T has been detected in East Asia widely and identified as having a biological function in cataracts." (PMID 32148946, 2020). "In addition, the CRYGD c.70C>A mutation was screened out in another three cataract patients (I:2, II:5 and III:1), and WFS1 c.1514G>C was screened out in another two iris coloboma patients (I:2, and II:5)." (PMID 32148946, 2020). "Cataracts have also been reported in Wolfram patients carrying biallelic WFS1 mutations, although this is not a feature of this syndrome, and dominant isolated congenital cataract has been described in members from an extended family carrying a specific heterozygous WFS1 mutation." (PMID 29112131, 2017). "The first signs of cataracts are present in Wfs1-ex5-KO232 rats at 3 months of age, and the incidence of cataracts increased during ageing." (PMID 28860598, 2017).